U2 (U2 spliceosomal RNA )
Synonyms: LOC124900916
Gene: Small nuclear RNA gene on chromosome 4 (25,250,545 to 25,250,639, forward strand). Ensembl gene ENSG00000278135.
Gene Ontology:
Molecular function: pre-mRNA branch point binding
Biological process: mRNA branch site recognition
Cellular component: U2 snRNP
Homologues: Orthologues: macaque U2 (71% identical), rabbit U2 (67% identical), dog U2 (60% identical). Paralogues in human: RNU2-2 (71% identical), U2 (71% identical), RNU2-17P (69% identical), RNU2-52P (69% identical), RNU2-56P (69% identical), RNU2-6P (69% identical), RNU2-36P (68% identical), RNU2-59P (68% identical), RNU2-29P (67% identical), RNU2-4P (67% identical), RNU2-5P (67% identical), RNU2-68P (67% identical), and 65 more.